RNU6-307P (RNA, U6 small nuclear 307, pseudogene)
Gene: Small nuclear RNA gene on chromosome 1 (174,996,524 to 174,996,629, forward strand). Ensembl gene ENSG00000252552.
Homologues: Orthologues: chimpanzee U6 (100% identical), macaque U6 (92% identical), pig U6 (66% identical), rat LOC120101207 (60% identical), mouse Gm55032 (58% identical). Paralogues in human: RNU6-698P (84% identical), RNU6-188P (83% identical), RNU6-83P (83% identical), RNU6-147P (82% identical), RNU6-266P (82% identical), RNU6-47P (82% identical), RNU6-1060P (81% identical), RNU6-116P (81% identical), RNU6-1227P (81% identical), RNU6-125P (81% identical), RNU6-1289P (81% identical), RNU6-15P (81% identical), and 1289 more.